PLA2R1 (phospholipase A2 receptor 1)
Diseases named in the same sentence as PLA2R1 in open-access papers (continued):
Sharing a sentence is not in itself a finding about the gene and the disease.
cancer (continued). "The data of this study indicate that the PLA2R1 is differentially expressed in mammary normal and cancer cells and that the cellular receptor expression is regulated by epigenetic mechanisms such as DNA methylation and histone acetylation." (PMID 26672991, 2015). "Analysis in the Oncomine database, a cancer microarray database allowing to perform differential expression analyses comparing most major types of cancer with respective normal tissues, shows that numerous cancers display an unusually low PLA2R1 mRNA level." (PMID 24657971, 2014). "As reported, PLA2R1 plays an important role in cancer suppression in a variety of cancers." (PMID 37345058, 2023). "The detailed role of PLA2R1 in tumorigenesis remains unclear considering heterogeneity of the observed data in different cell lines of the same cancer type." (PMID 30542512, 2018). "We propose a revised clinical workup flow for patients with MN that recommends assessment of kidney biopsy for PLA2R1 and THSD7A antigen expression, screening for circulating anti-podocytes antibodies, and assessment for secondary causes, especially cancer, in patients with THSD7A antibodies." (PMID 29511687, 2018). "Patients with PLA2R1-associated MN and no malignancy were significantly younger, had better preserved renal function and had less tubulointerstitial fibrosis compared to PLA2R1-ab positive patients with malignancy." (PMID 30619370, 2018). "The findings of this study demonstrate that the PLA2R1 is differentially expressed amongst mammary normal and cancer cells, and confirm the importance of epigenetic mechanisms such DNA methylation and histone modification in the regulation of PLA2R1 transcript levels." (PMID 26672991, 2015). "However, detailed functions and mechanisms of PLA2R1-mediated signalling in normal and different cancer cells remain to be elucidated." (PMID 26672991, 2015). "In our cohort, patients with PLA2R1-associated MN with malignancy were significantly older than those patients without malignancy, which might suggest that a number of tumors might be age-related." (PMID 30619370, 2018). "Some of the top DNA hypermethylated IRGs, such as BMP8B, PLA2R1, MSX1, DGCR5, and MT1G, were previously identified as tumor suppressors in gastric and other cancers." (PMID 32841292, 2020). "Our data indicate complex and highly cell-specific functions of PLA2R1 exhibiting both pro-oncogenic (PC-3) and tumour-suppressive characteristics (LNCaP and MDA-MB-453) in different cancer cells." (PMID 30542512, 2018). "PLA2R1 ectopic overexpression in originally PLA2R1 negative cancer cells induces apoptosis and onco-suppressing role independently of sPLA2 binding." (PMID 35333675, 2022). "Testing for THSD7A antigen is only needed in cases of suspected primary MN that is negative for PLA2R1 antigen or cases suspected of having cancer-related MN." (PMID 29511687, 2018). "Accordingly, an intensive search for cancer should be carried out in MN patients without anti-PLA2R1 antibodies, with prevailing IgG1/IgG2 deposits, or with more than eight inflammatory cells per glomeruli at renal biopsy." (PMID 26498294, 2016). "Considering that DNA methylation is an important regulator of gene transcription during carcinogenesis, in the current study we analyzed the PLA2R1 expression, PLA2R1 promoter methylation, and selected micro RNA (miRNA) levels in normal human mammary epithelial cells (HMEC) and cancer cell lines." (PMID 26672991, 2015). "Interestingly, a higher PLA2R1 mRNA level was found in VHL functional ACHN cells than in any of the VHL nonfunctional cancer cell lines." (PMID 24657971, 2014). "Whether our findings may or may not be transferred to patients with PLA2R1-ab and THSD7A-ab negative MN, especially in those patients with malignancies, who show a negative IgG4 staining in the biopsy remains an open question." (PMID 30619370, 2018).
tumor (43 papers, 2008 to 2025). "In vitro analysis revealed an anti-proliferative phenotype associated with PLA2R1 re-expression, suggesting a tumour-suppressive function of PLA2R1." (PMID 32493972, 2020). "Considering high selective pressure and mutation rate during tumour development, and potential metabolic burden caused by PLA2R1-overexpression, it seems unreasonable to assume that PLA2R1 has a tumour-suppressive function in PC-3." (PMID 30542512, 2018). "Presumably, PLA2R1-linked clonogenicity (stemness) of LNCaP subpopulations is a crucial factor required for tumour development in vivo." (PMID 30542512, 2018). "Together, these data provide the first evidence that increasing the PLA2R1 level causes tumor-suppressive effects in RCC." (PMID 24657971, 2014). "In conclusion, our study report novel findings showing that PLA2R1 is repressed in RCC by the loss of VHL tumor suppressor and the activation of the oncogenic HIF2α-c-MYC pathway and that repression favors RCC tumorigenecity." (PMID 24657971, 2014). "We have previously discovered that in normal human cells, loss of the phospholipase A2 receptor (PLA2R1) delays senescence or favors senescence escape, depending on the stress, senescence being a tumor suppressive pathway." (PMID 24657971, 2014). "First and foremost, loss of Pla2r1 in mice resulted in increased tumor formation in old animals." (PMID 33594040, 2021). "This pro-senescent activity can also be beneficial, as PLA2R1-mediated senescence has been shown to inhibit spontaneous tumor formation during aging by eliminating damaged cells." (PMID 41497980, 2025). "We discovered that the expression of PLA2R1 was lower in the tumor tissues than in para-cancerous tissues (χ2 = 37.0, p < 0.01)." (PMID 37345058, 2023). "The expression of PLA2R1 was lower in the tumor tissues than in para-cancerous tissues (χ2 = 37.0, p < 0.01)." (PMID 37345058, 2023). "Two DEPs (SLC25A15 and PLA2R1) were also validated their expression difference between tumor and peritumoral tissues using IHC method." (PMID 36106120, 2022). "Several reports demonstrated that PLA2R1 has an important role in regulating tumor-suppressive responses via activation of Janus kinase 2, yet these effects do not seem to be related to its sPLA2 binding properties." (PMID 35887380, 2022). "Phospholipase A2 Receptor 1 (PLA2R1) is a transmembrane protein of the mannose receptor family that can regulate several tumor-suppressive responses via JAK2 activation." (PMID 36106120, 2022). "In this study, we aimed at deciphering and investigating the role of the PLA2R1 protein during aging-induced tumor formation using aged mice, normal human cells and large human datasets." (PMID 33594040, 2021). "The transmembrane protein PLA2R1 (phospholipase A2 receptor) promotes cellular senescence, which can inhibit oncogene-induced tumor initiation." (PMID 33594040, 2021). "In conclusion, our work sheds light on the tumor suppressive effect of PLA2R1 during aging and its downstream effectors: ROS, PARP1, and DNA damage and its downstream tumor suppressive pathway." (PMID 33594040, 2021). "In vitro analysis showed that the PLA2R1 re-expression and up-regulation of protein synthesis in transfected Jurkat cells had a negative impact on cellular proliferative behaviour, suggesting an important tumour-suppressive role of PLA2R1 in childhood ALL." (PMID 32493972, 2020). "PLA2R1 was found to endorse several tumor suppressive responses, including cellular senescence and apoptosis." (PMID 32751713, 2020). "Emerging results also suggest a role of PLA2R1 as a driver of cellular senescence contributing to progeria and tumor initiation processes in mice." (PMID 32424163, 2020). "Similar to many tumour-suppressors, PLA2R1 was down-regulated in breast and kidney cancers, and in melanoma cells." (PMID 30542512, 2018). "Further immunohistochemical analysis of tumour xenografts has to be conducted to investigate the interactions of PLA2R1 in vivo." (PMID 30542512, 2018).
tumor (continued). "Alternatively, PC-3 Ctrl xenografts exhibited faster tumour growth compared to PC-3 KD cells, suggesting a pro-oncogenic effect of endogenous PLA2R1 expression." (PMID 30542512, 2018). "In LNCaP xenografts, PLA2R1-dependent regulation of clonogenicity appeared to outweigh the receptor’s pro-oncogenic properties, resulting in decreased tumour growth, supporting the tumour-suppressive role of PLA2R1." (PMID 30542512, 2018). "PLA2R1 is downregulated in malignant PTC versus benign disease, and appears to suppress tumorigenesis by activating the tyrosine kinase JAK2." (PMID 27633254, 2016). "Recently, PLA2R1 was identified as potential tumour suppressor that controls replicative- and stress-induced senescence." (PMID 26672991, 2015). "In 786-O and ACHN derived tumors, constitutive expression of PLA2R1 was found to affect tumor growth both by decreasing cell proliferation (as estimated by Ki-67 staining) and increasing cell death (as estimated in TUNEL assays)." (PMID 24657971, 2014). "Our results describe for the first time an oncogenic pathway leading to PLA2R1 transcriptional repression and the importance of this repression for tumor growth." (PMID 24657971, 2014). "These tumor suppressive effects of PLA2R1 are at least in part mediated by increased JAK2 activity and increased ROS production." (PMID 24657971, 2014). "PLA2R1 expression correlates with loss of VHL tumor-suppressor function, and restoring VHL expression is sufficient to restore PLA2R1 expression in RCC-derived cell lines." (PMID 24657971, 2014). "786-O-derived tumors grew rapidly in mice, but this tumor growth was slowed down when PLA2R1 was constitutively expressed." (PMID 24657971, 2014). "Having observed that PLA2R1 is lost in human RCC samples and that PLA2R1 deregulation strongly impacts RCC tumor growth, we next investigated the mechanism regulating PLA2R1 expression in RCC." (PMID 24657971, 2014). "PLA2R1 knockdown was found to increase tumor growth significantly, the average tumor volume reaching about three times that of control tumors." (PMID 24657971, 2014). "The influence of PLA2R1 on tumor cell function has been partially reported." (PMID 37345058, 2023). "Additionally, PLA2R1 is able to enhance the tumor suppressing responses, such as apoptosis, senescence, or transformation suppression." (PMID 34112138, 2021). "In this study, we demonstrated the role of PLA2R1 in tumor suppression during aging." (PMID 33594040, 2021). "To investigate whether PLA2R1 regulates spontaneous tumor formation during aging, we generated mice cohorts composed of wild type (WT) and Pla2r1 knockout littermates." (PMID 33594040, 2021). "The increased tumour growth of PC-3 cells with endogenous PLA2R1 expression in vivo could therefore indicate PLA2R1 effects in CD44+/CD24- subpopulation that require further confirmation." (PMID 30542512, 2018). "The tumour-suppressive role of PLA2R1 was indicated in various cell types." (PMID 30542512, 2018). "The CSC role in regulation of PLA2R1 expression is unclear, however, it might be reflected by a decreased clonogenicity of LNCaP-PLA2R1 cells in vitro and weakened tumour growth in vivo." (PMID 30542512, 2018). "LNCaP-PLA2R1 tumours grew slower supporting putative tumour-suppressive properties of PLA2R1." (PMID 30542512, 2018). "PLA2R1 associated activation of JAK2, estrogen related receptor α (ERRα) signalling, and mitochondrial apoptosis pathways were presented as mediators of the PLA2R1 tumour-suppressive function in MDA-MB-453 cells." (PMID 30542512, 2018). "In this study, the tumour-suppressive influence of PLA2R1 was confirmed." (PMID 30542512, 2018). "Recent studies uncovered a novel tumour suppressive function of PLA2R1." (PMID 26672991, 2015).
tumor (continued). "Together these results strongly support a tumor-suppressive activity of PLA2R1." (PMID 24657971, 2014). "To examine whether PLA2R1 might exert tumor-suppressive activity in RCC, we first analyzed transcript-level PLA2R1 expression in normal and RCC tissue samples." (PMID 24657971, 2014). "We show here that PLA2R1 is lost in RCC and that this loss might be an important event increasing RCC growth as its decrease accelerates tumor growth in nude mice." (PMID 24657971, 2014). "As PLA2R1 levels strongly decreased in RCC, we next examined whether PLA2R1 down regulation might influence RCC tumor growth." (PMID 24657971, 2014). "The M-type phospholipase A2 receptor (PLA2R1) plays a crucial role in several signaling pathways and may act as tumor-suppressor." (PMID 23217014, 2012). "Therefore, further investigation is warranted into whether the tumour-suppressive behaviours of PLA2R1 re-expression will be repeated in B-ALL cell lines and primary blast cells." (PMID 32493972, 2020). "(iv) The absence of anti-PLA2R1 in patients without immunosuppressive treatment and/or the absence of PLA2R1 expression within immune deposits should prompt systematic testing for a secondary cause of MN, including neoplasms, in particular in patients over the age of 60." (PMID 29511687, 2018). "In addition, PLA2R1-deficient mice displayed increased sensitivity to RAS-induced tumourigenesis by facilitating oncogenic stress-induced senescence escape in vivo, highlighting the role of the receptor as tumour suppressor." (PMID 26672991, 2015). "In addition, PLA2R1 has recently been described as an important protein in kidney physiopathology, we have then decided to investigate whether it might play a tumor-suppressive role in kidney cancer." (PMID 24657971, 2014). "Comparative analyses of these DEPs revealed downregulated expression of specific proteins with well-established links to tumor metastasis, such as SLC25A15, DIRAS2, PLA2R1, and MTARC1." (PMID 36106120, 2022). "In conclusion, our results suggest that PLA2R1 suppresses aging-induced tumors by repressing PARP1, via a ROS–Rb signaling axis, and inducing DNA damage and its tumor suppressive responses." (PMID 33594040, 2021). "It was described that PLA2R1-knockdown in MDA-MB-436 results in increased sizes of soft agar colonies, supporting the tumour-suppressive role of the receptor." (PMID 30542512, 2018). "Next, control or PLA2R1 knockdown ACHN cells were injected subcutaneously into nude mice and tumor growth was monitored for 47 days after grafting." (PMID 24657971, 2014). "Suggestively, the functional interaction between PLA2R1 and β1 integrin may favour ITGA2 in LNCaP cells due to the lack of ITGA1-expression resulting in a decreased tumour growth and tumour-suppressive role of PLA2R1 in vivo." (PMID 30542512, 2018). "We suggest that PLA2R1-regulated expression of FN1, TWIST1, and CDK6 might be accountable for the cell type-dependent impact of PLA2R1 in tumour cell survival and growth." (PMID 30542512, 2018). "Western blot analysis of tumour xenografts confirmed PLA2R1 synthesis of LNCaP-PLA2R1 and PC-3 Ctrl cells, while no PLA2R1 expression was detectable for LNCaP-Ctrl and PC-3 KD tumour specimens." (PMID 30542512, 2018). "No variation in expression between the tumours and normal mucosa was observed for PLA2G1B, PLA2G2A, PLA2G2F, PLA2G10, PLA2G12A and PLA2G12B and for the M-type sPLA2 receptor (PLA2R1)." (PMID 18212756, 2008).
kidney disease (29 papers, 2012 to 2025). "Associated variants were found in and around genes encoding uPAR (PLAUR), its ligand uPA (PLAU), the kidney-disease-associated gene PLA2R1 as well as genes with relations to glycosylation, glycoprotein biosynthesis, and the immune response." (PMID 34079037, 2021). "Nowadays, there is no generally accepted standard schedule for RTX administration in renal diseases: B-cell driving therapy, conventional therapy dose, or administration driving by ANCAs or PLA2R1 according to etiology of renal disease." (PMID 31904761, 2020). "It is well-reported that increased suPAR has strong associations with CKD14–17, though it is unknown how suPAR and PLA2R1 are related to each other in respect to kidney disease." (PMID 34079037, 2021). "Nonetheless, the identification of PLA2R1 as a top-upregulated gene in CKD, AKI, and DN suggests that PLA2R1 may play a general role in causing podocyte injury, which contributes to proteinuria in these kidney diseases." (PMID 40149392, 2025).
metabolic disorders (1 paper, 2023). "Overall, our results support that PLA2R1 regulates some age‐related phenotypes during physiological aging or following a Western diet and opens new perspectives to improve our understanding of the biology of aging as well as a new mechanism contributing to metabolic disorders." (PMID 37667516, 2023). "As cellular senescence is involved in metabolic disorders such as NAFLD and as these disorders lead to signs of accelerated aging, we wondered whether the loss of Pla2r1 could impact cellular senescence, glucose regulation, and liver alterations caused by Western diets (WD)." (PMID 37667516, 2023).
PLA2R1 also shares sentences with these, for which no sentence is quoted: glomerular diseases (19 papers); Hypoalbuminemia (13); infection (11); minimal change disease (11); Nephropathy (10); glomerulopathy (8); Glomerular sclerosis (7); focal segmental glomerulosclerosis (6); diabetic nephropathy (5); IgG4-related disease (5); syphilis (5); type 2 diabetes mellitus (5); COVID-19 (4); end-stage renal disease (4); Hypercholesterolemia (4); interstitial nephritis (4); allergic disease (3); ANCA-associated vasculitis (3); autoimmune thyroid disease (3); dyslipidemia (3); Hashimoto thyroiditis (3); ischemic stroke (3); lung carcinoma (3); psoriasis (3); Stroke (3); thyroid disease (3); viral infections (3); amyloidosis (2); Crohn disease (2); diabetic retinopathy (2).
A further 114 diseases each share a sentence with PLA2R1 in 2 papers or fewer.